SLC52A1 (solute carrier family 52 member 1)
Description:
Plasma membrane transporter mediating the uptake by cells of the water soluble vitamin B2/riboflavin that plays a key role in biochemical oxidation-reduction reactions of the carbohydrate, lipid, and amino acid metabolism. Humans are unable to synthesize vitamin B2/riboflavin and must obtain it via intestinal absorption. (Microbial infection) May function as a cell receptor to retroviral envelopes similar to the porcine endogenous retrovirus (PERV-A).
Synonyms: huPAR-2; hRFT1; GPR172B; PAR2; RFT1; FLJ10060; GPCR42; RFVT1; RBFVD
Tractability: Antibody: UniProt places it where antibodies can reach, with high confidence; its Gene Ontology location is reachable by antibodies, with high confidence; UniProt predicts a signal peptide or a membrane-spanning region. PROTAC: ubiquitination databases record sites on it.
Gene: Protein-coding gene on chromosome 17 (5,032,600 to 5,052,009, reverse strand). Ensembl gene ENSG00000132517.
Subcellular location: Cell membrane
Pathways (Reactome):
Metabolism: Vitamin B2 (riboflavin) metabolism
Gene Ontology:
Molecular function: protein binding; riboflavin transmembrane transporter activity; urate transmembrane transporter activity
Biological process: riboflavin transport; urate transport; riboflavin metabolic process
Cellular component: plasma membrane
Genetic constraint (gnomAD): Loss-of-function variants: 20 observed, 25.92 expected, observed/expected ratio (o/e) 0.77, 90% interval 0.54 to 1.12. The upper end of that interval is the gene's LOEUF score, 1.12, which puts it in group 4 of 6, group 1 being the genes least tolerant of losing a copy. Missense variants: 528 observed, 581.09 expected, observed/expected ratio (o/e) 0.91, 90% interval 0.85 to 0.98. Synonymous variants: 260 observed, 267.95 expected, observed/expected ratio (o/e) 0.97, 90% interval 0.88 to 1.08.
Gene-disease validity (ClinGen):
ClinGen rates the evidence that SLC52A1 causes each of these diseases.
maternal riboflavin deficiency (autosomal dominant): Moderate.
Homologues: Orthologues: chimpanzee SLC52A1 (99% identical), macaque SLC52A1 (97% identical), dog SLC52A2 (85% identical), mouse Slc52a2 (81% identical), rat Slc52a2 (75% identical), zebrafish slc52a2 (50% identical), tropical clawed frog slc52a1 (48% identical), Drosophila melanogaster Rift (34% identical), Caenorhabditis elegans rft-1 (30% identical), Caenorhabditis elegans rft-2 (29% identical). Paralogues in human: SLC52A2 (86% identical), SLC52A3 (40% identical).
Diseases named in the same sentence as SLC52A1 in open-access papers:
SLC52A1 is named in the same sentence as 25 diseases in open-access papers, as found by Europe PMC text mining. Sharing a sentence is not in itself a finding about the gene and the disease. The quoted sentences say what the papers report.
multiple acyl-CoA dehydrogenase deficiency (2 papers, 2022 to 2025). "Similarly, heterozygous mutations in SLC52A1 can cause transient symptoms of multiple acyl-CoA dehydrogenase deficiency (MADD) in newborns, especially when maternal Rf levels are insufficient during pregnancy." (PMID 40444179, 2025).
viral infection (2 papers, 2009 to 2025). "Alternatively, even if SLC52A1 is expressed in relatively small amounts, it may function as a receptor for viral infection." (PMID 40574751, 2025). "Furthermore, the results of the present study do not clarify the relationship between SLC52A1/2 gene polymorphisms and susceptibility to viral infection." (PMID 40574751, 2025). "Viral infection using the PERV-A and PERV-A/C Env-pseudotyped viruses was confirmed in MDTF-chSLC52A2, MDTF-huSLC52A2, MDTF-chSLC52A1, and MDTF-huSLC52A1 cells, thereby indicating that chimpanzee and human SLC52A2 and SLC52A1 expression confers susceptibility to infection with pseudo-typed PERV." (PMID 40574751, 2025). "Chimpanzee SLC52A2-, human SLC52A2-, chimpanzee SLC52A1-, and human SLC52A1-expressing MDTF cells, designated MDTF-chSLC52A2, MDTF-huSLC52A2, MDTF-chSLC52A1, and MDTF-huSLC52A1, respectively, were characterized by permissiveness to CERV-1 Env-pseudotyped virus infection, whereas MDTF cells were not." (PMID 40574751, 2025).
acyl-CoA dehydrogenase deficiency (1 paper, 2023). "While newborns and infants with SLC52A1 variants mainly showed a multiple acyl-CoA dehydrogenase deficiency-like presentation, individuals identified in adulthood were usually clinically asymptomatic." (PMID 37510312, 2023).
amyotrophic lateral sclerosis (1 paper, 2025). Amyotrophic lateral sclerosis (ALS) is a neurodegenerative disease characterized by progressive muscular paralysis reflecting degeneration of motor neurons in the primary motor cortex, corticospinal tracts, brainstem and spinal cord. "In our AD EA TWAS, we also identified genes associated with other neurological and autoimmune diseases, including Parkinson’s disease (CYB561 and SLC25A39), Crohn’s disease (ATG16L1), Amyotrophic lateral sclerosis (SIGLEC9), and Riboflavin Transport Deficiency (SLC52A1)." (PMID 40141087, 2025).
Brown-Vialetto-Van Laere syndrome (1 paper, 2014). "In addition, a deletion in SLC52A1, coding for a third riboflavin transporter, RFVT1 (formerly RFT1), was reported in a case of maternal riboflavin deficiency without an associated Brown-Vialetto-Van Laere syndrome phenotype." (PMID 24253200, 2014).
riboflavin deficiency (1 paper, 2023). "Given that blood concentrations of riboflavin are commonly decreased during pregnancy, pregnant individuals with SLC52A1 mutations may require higher riboflavin intake to avoid gestational riboflavin deficiency." (PMID 37845732, 2023). "Notably, in otherwise healthy females who become pregnant, transient neonatal riboflavin deficiency has been shown to be associated with a rare genetic variant of SLC52A1 (rs141935493) in the mother rather than the foetus." (PMID 37845732, 2023).
infection (4 papers, 2007 to 2025). The state of being infected such as from the introduction of a foreign agent such as serum, vaccine, antigenic substance or organism. "The ectopic expression of human and chimpanzee SLC52A2 and its related SLC52A1 in heterogenic cells confers susceptibility to infection by CERV1 and porcine endogenous retrovirus (PERV)." (PMID 40574751, 2025). "Since it was confirmed that NCMDF cells have a serine at position 109 of SLC52A2, it is thought that SLC52A1 functions as the entry receptor for PERV-A/C infection in NCMDF cells." (PMID 40574751, 2025). "The infection with a pseudo-virus showed that MDTF cells expressing human SLC52A2 and chimpanzee SLC52A1 had a higher infection titre." (PMID 40574751, 2025). "Notably, CERV1 infection is observed in human cell lines that express human SLC52A2 abundantly but hardly express human SLC52A1." (PMID 40574751, 2025). "However, the amount of receptor expression on the cell surface has not been measured, so at present, the preference for SLC52A1/2 is unknown for CERV1 infections." (PMID 40574751, 2025).
cancer (3 papers, 2020 to 2024). A tumor composed of atypical neoplastic, often pleomorphic cells that invade other tissues. "Similarly relevant for the anti-cancer manipulation of vitamin B2 supplies is the recently described riboflavin transporters SLC52A1-334." (PMID 32895367, 2020). "The remaining signature genes, CPXM2, ENPP5, SAMD13, SLC52A1, ZNF682, ZNF835, ZNF571-AS1 and U91328.1, have not been related to carcinoma, yet." (PMID 33672117, 2021).
metabolic disorder (2 papers, 2023 to 2024). "Deficiency in riboflavin transporter 1 is another quite rare metabolic disorder due to autosomal dominant pathogenic variants in the SLC52A1 gene (OMIM #615026)." (PMID 39063339, 2024). "Riboflavin transporter 1 (RFVT1) deficiency is an ultrarare metabolic disorder due to autosomal dominant pathogenic variants in SLC52A1." (PMID 37510312, 2023).
SLC52A1 also shares sentences with these, for which no sentence is quoted: tumor (2 papers); autoimmune disease (1); breast carcinoma (1); breast tumor (1); cranial neuropathies (1); Crohn disease (1); diabetes (1); Encephalopathy (1); Hyperammonemia (1); lung carcinoma (1); melanoma (1); optic atrophy (1); Parkinson disease (1); Respiratory insufficiency (1); Sensorimotor neuropathy (1); sensory ataxia (1).